MDM2 (MDM2 proto-oncogene)
Diseases named in the same sentence as MDM2 in open-access papers (continued):
Sharing a sentence is not in itself a finding about the gene and the disease.
leukemia (continued). "Since chemotherapy induces the senescence of leukemia cells partly via P21, combined with our discovery that PSMB10 induces MDM2-mediated degradation of P21 protein, we conclude that the increased PSMB10 also impedes chemotherapy drug-induced P21-dependent senescence of AML cells." (PMID 40462177, 2025). "MDM2-specific TCR-CTL efficiently killed several human tumor and leukemia targets." (PMID 35356211, 2022). "All these data proved that the rationally designed peptide drug PMIBcr/Abl‐R6 was able to inhibit Ph+ leukemia cells, MDM2 targeting improved its efficacy, and no off‐target toxicity was observed." (PMID 35239999, 2022). "In Ph+ leukemia cases, either resistant to TKIs or not, PMIBcr/Abl‐R6 is thought to be able to kill Ph+ leukemia cells by dual targeting of both, MDM2 and Bcr/Abl." (PMID 35239999, 2022). "Furthermore, combination therapy with a JAK3 inhibitor (tofacitinib) and a MDM2 inhibitor (idasanutlin) reduces the Phf6 KO and JAK3M511I leukemia burden in vivo." (PMID 34465864, 2022). "APC and MDM2 in the MDM2:APC cross-talk are both tumor suppressors; they co-regulate DNA polymerase- β which is reported to be hyper-activated in a cis-diamminedichloroplatinum(II) resistant P388 murine leukemia cell line." (PMID 25599599, 2015). "So far, the focus of interest in MDM2 overexpression has been on drug-resistant childhood ALL cases, whereas its potential relevance in E/R-positive cases has been largely disregarded because of the comparably favorable outcome of these leukemias." (PMID 24240203, 2014).
leukemia (continued). "The E/R-induced upregulation of MDM2 in Ba/F3 murine pro-B cells indicates that this occurs merely as a function of the fusion gene early on during leukemia development and is found in the absence of secondary aberrations." (PMID 24240203, 2014). "High levels of MDM2 expression can still be observed even in malignancies without MDM2 gene amplification, as occurs in leukemia." (PMID 24968304, 2014). "MDM2 (mouse double minute 2; the human gene is also known as HDM2) is an oncogene which is expressed at high levels in numerous human cancers, including those of the breast, lung, colon, pancreas, and hematological malignancies lymphomas and leukemias." (PMID 24236052, 2013). "Epicatechin and scopoletin induce apoptosis in leukemia (Jurkat, WEHI-3b) and lung adenocarcinoma (A549) through caspase-3/8 activation, G0/G1 arrest, and downregulation of tumor proliferation genes (EGFR, MDM2, RAF1, mTOR), while enhancing immune responses and reducing COX-2 expression." (PMID 41346617, 2025). "More and more studies have demonstrated that MDM2 inhibitors can combine with various agents, including PI3K/AKT, RAF/MEK/ERK signaling pathways inhibitors and CDK inhibitors, anti-CD20 antibodies, and anti-PD-L1/PD-1 agents to induce apoptosis in various types of cancers/leukemia cells." (PMID 39144622, 2024). "MTOR/Akt inhibitors are synergistic with MDM2 inhibitors in inducing apoptosis in leukemias but whether this synergy is autophagy related has not been determined." (PMID 26440941, 2015). "We speculate that this may be due to the differential effect of MdmX on Mdm2 protein stability, that is, MdmX has a crucial role to stabilize Mdm2 proteins in leukemia cells but is not so critical in colon cancer cells." (PMID 26720344, 2015). "Also, high levels of MDM2 expression can be observed even in malignancies without MDM2 gene amplification, as occurs in leukemia." (PMID 25888903, 2015). "Taken together, these results suggest that MDM2 may be a therapeutic target to increase TKI-mediated apoptosis and that combining PI3K/mTOR inhibitor and TKI may prove an effective novel therapeutic strategy in TKI-resistant BCR-ABL1 positive leukemia." (PMID 24349524, 2013).
hepatocellular carcinoma (98 papers, 1999 to 2026). A malignant tumor that arises from hepatocytes. "In hepatocellular carcinoma cells, the overexpression of iASPP has been associated with even worse patients’ overall survival than MDM2 overexpression." (PMID 36374405, 2023). "The findings from different areas support that MDM2 is significantly associated with increased risk of hepatocellular carcinoma." (PMID 24955377, 2014). "MDM2 SNP309 G allele is a susceptibility gene for the development of viral hepatitis-related hepatocellular carcinoma." (PMID 24955377, 2014). "However, in liver‐related diseases like hepatocellular carcinoma, MDM2 overactivation has been reported to be associated with hepatocellular carcinoma occurrence." (PMID 36840487, 2023). "Additionally, it has been illustrated that MDM2 expression deficiency can protect against hepatocellular carcinoma development via dampening the antioxidant response and apoptosis." (PMID 36840487, 2023). "Studies have shown that the 40 bp missing genotype (SS) for the mdm2 rs3730485 locus may be a risk factor for uterine fibroids; other studies also suggested that the SS type of this locus was a risk factor for hepatocellular carcinoma." (PMID 29892419, 2018). "Similar findings have been reported in previous studies, including hepatocellular carcinoma associated with chronic hepatitis C, gastric carcinoma, and sporadic endometrial carcinoma, suggesting an interaction of MDM2 SNP309, infectious factor, and hormone factor." (PMID 21619694, 2011). "In a recent study on an experimental mouse liver cancer model, diosmin decreased the growth of HA22T cells in human hepatocellular cancer by downregulating the PI3K–Akt–MDM2 signaling pathway and triggering G2/M cell cycle arrest." (PMID 39554345, 2024). "Another study on hepatocellular carcinoma (HCC) identified the significant role of MDM2 inhibitor (SP141) in the repression of metastasis." (PMID 37314603, 2023). "Our recent clinical study has demonstrated that high expression levels of NFAT1 and MDM2 are independent predictors of a poor prognosis in patients with hepatocellular carcinoma." (PMID 32397368, 2020).
hepatocellular carcinoma (continued). "Our previous studies revealed that GADD45α is a liable protein, which undergoes MDM2-dependent constitutive ubiquitination and degradation in resting HepG2 hepatoma cells." (PMID 30177839, 2019). "Further, it was demonstrated that HOXB5 could induce the expression of murine double minute 2 oncogene (MDM2) in hepatoma cells through ERK/MDM2 signaling." (PMID 34617205, 2022). "Indeed, overexpression of MDM2 has been previously found in many cancer types including hepatocellular carcinoma, and MDM2 protein levels are also elevated in HepG2 cells." (PMID 35802572, 2022).
hepatocellular carcinoma (continued). "However, the E3 ligase MDM2 protein levels were also increased in hepatoma cells lines (lower), which support its oncogenic role in tumorigenesis." (PMID 26336826, 2015). "However, the decrease of RAD6 protein levels likely determined the upregulation of ASF1A and H3K56Ac levels although MDM2 levels were increased in hepatoma cell lines." (PMID 26336826, 2015). "The overexpression was not caused by MDM2 mutations formerly found in hepatocellular carcinoma since none of the three samples accumulating MDM2 demonstrated corresponding changes." (PMID 11953887, 2002). "Since alterations of the MDM2/P14ARF system have been observed in many human tumours – including hepatocellular carcinoma – they may also be present in cirrhotic liver thus representing early events in the pathogenesis of the liver." (PMID 11953887, 2002). "It has been shown that MDM2 oncoprotein ovexpression is frequently observed in hepatocellular carcinoma (HCC), Thus, MDM2's negative regulation on SPOP adds another layer of impact of MDM2 overexpression in HCC." (PMID 38308184, 2024). "Up-regulation of MDM2 after AFB1 exposure has been observed in human hepatocellular carcinoma (HCC) cells, rats, swine, and in our previous study of turkey poults." (PMID 26751476, 2016). "Notably, MA242, an MDM2 inhibitor discovered in our lab, has unique mechanisms of action different from the existing MDM2 inhibitors under preclinical and clinical investigations and shows significant antitumor activity in preclinical pancreatic cancer and hepatocellular carcinoma (HCC) models." (PMID 40046748, 2025). "The overexpression of the Mdm2 oncoprotein transcript after PBDE exposure seen in the adult rat in these studies, has been observed to frequently occur in hepatocellular carcinoma (HCC)." (PMID 36687508, 2022). "We first investigated the correlation between RAD6 and MDM2 protein levels and ASF1A and H3K56Ac levels in the normal liver cell line HL-7702 and in different hepatoma cell lines (SMMC, HepG2, Hep3B and Huh7)." (PMID 26336826, 2015).